IGF1 (insulin like growth factor 1)
Diseases named in the same sentence as IGF1 in open-access papers (continued):
Sharing a sentence is not in itself a finding about the gene and the disease.
cancer (continued). "Aberrant expression or regulation of IGF1 and IGFBP3 has been demonstrated to facilitate carcinogenesis and have an effect on cancer prognosis." (PMID 27976731, 2016). "It was identified that high levels of insulin and IGFs can promote cancer development through insulin/IGF axis, and especially that IGF-1 plays an important role in the inhibition of apoptosis and promotion of cell-cycle progression." (PMID 27509022, 2016). "Overtime it was suggested that diet-induced regulation of insulin and its closely related hormone, Insulin-like growth factor 1 (IGF-1), were main events involved in protection against cancer incidence." (PMID 27689327, 2016). "The insulin-like growth factors (IGFs), IGF-1 and IGF-2, are ligands that bind to IGF receptor (IGF-1R,) and regulate cancer cell proliferation, survival, and metastasis." (PMID 25866791, 2015). "Up-regulated genes due to the down-regulation of microRNAs by EGF, bFGF, and IGF-1 treatment were predicted to target EGFR, FGFR, and IGFR, respectively, via cytokine-cytokine receptor interaction in the cancer pathway." (PMID 25938966, 2015). "Combining an anti-IGF1R antibody with MEDI-573 offers a better antitumor effect because of greater inhibition of IGF1 and IGF2 signaling in cancer cells and tumor angiogenesis is inhibited." (PMID 25699021, 2015). "Particularly, many cancer-related genes including CDH5, BVES, CX3CL1, FGFR1, IGF1 and CD40 were identified in SIN_D." (PMID 25774687, 2015). "Metabolic stresses including Insulin/IGF-1 enhance the expression of TRB3 in a diversity of human tumour tissues and cancer cells." (PMID 26268733, 2015). "Amongst the many factors in platelet granules, IGF1 has received considerable attention, due to its involvement in HCC growth and prognosis and as a possible target of anti-cancer and anti-HCC therapies." (PMID 26329608, 2015). "Several clinical and experimental studies have reported that increased circulating IGF-1 levels and increased expression of IGF-1 and IGF-1R in tumor tissues are involved in the development of these malignant tumors." (PMID 25329702, 2014). "IGF-1 and insulin increased the proportion of cells with metabolically active mitochondria (cell viability) of stromal and cancer cells by between 13 and 55% (HMEC-1 in high glucose with insulin and WiDr in high glucose with IGF-1, respectively)." (PMID 24396438, 2014). "The result that low serum IGF-1 levels were associated with poor prognosis appears to be paradoxical because high IGF-1 levels and subsequent activation of the IGF system have been known as relevant signaling alterations in various cancers." (PMID 24595361, 2014). "Insulin like-growth factor-1 (IGF-1) reflects hepatic synthetic function and plays a major role in the development and progression of various cancers." (PMID 24595361, 2014). "As cancer risk rises exponentially with age and is the second leading cause of mortality in adult US population (CDC/NCHS National Vital Statistics System, 2010), reducing its incidence through inhibition of IGF-1 action may have a major impact on morbidity and mortality in the elderly." (PMID 24618355, 2014). "The release of factors stimulating proliferation of cancer cells, including epidermal growth factor (EGF), platelet-derived growth factor (PDGF), and insulin-like growth factor 1 (IGF-1), is seen as another mechanism." (PMID 24363760, 2013). "IGF-1 and IGF-1R both have been shown to be upregulated in multiple cancer cell types, affecting proliferation, differentiation, and metastasis." (PMID 24103397, 2013). "Binding of ganitumab inhibited the high-affinity interaction of IGF-1 and IGF-2 required to activate IGF1R in cells engineered for IGF1R hypersensitivity and in human cancer cell lines, resulting in complete blockade of ligand-induced cellular proliferation." (PMID 23383308, 2013). "Akt is activated by IGF-1/phosphatidyl inositol–3-kinase (PI3K) signalling, and deregulation of this signalling contributes to cancer." (PMID 23300147, 2013).
cancer (continued). "In this study using primary tumor tissue and cancer cells from patients, we showed striking over-expression of IGF-IR and IGF-1 in comparison to normal ovarian tissue samples." (PMID 24103397, 2013). "It is possible, that elimination of cells by apoptosis protects OSE from cancer development and corresponds to the lower incidence of cancer in GHR-KO mice, with very low levels of IGF-1 in circulating plasma." (PMID 24063422, 2013). "Among the IGF family proteins, IGF-1, IGF-1R and IGF-2 are positively correlated to cancer formation." (PMID 23071652, 2012). "The type 1 insulin-like growth factor receptor and its ligands, IGF1 and IGF2, are upregulated in a variety of human cancers." (PMID 22401581, 2012). "The IGF-1 pathway, whose genes IGF1R, IGF-1 and IGFBP-3 are among the target genes of the differentially expressed miRNAs, plays a critical role in cancer development, including ES." (PMID 22429812, 2012). "Overexpressed genes in the PP adipose tissue of cancer patients that are involved in cell cycle and proliferation include PLCB1, that modulates cyclin D3 and CDK4 in response to the IGF-1 mitogenic stimulus or TPPP3, that regulates G2-M and G1-S transitions." (PMID 23009291, 2012). "The stimulation by many growth factors, including IGF-1, PDGF, EGF, and TGF-β, has been shown to induce the expression of VEGF-C in malignant tumors." (PMID 22496919, 2012). "In cancer cells with high levels of IGF1R/IR HRs, IGF1 and IGF2 activate various downstream signaling pathways through heterodimeric receptors rather than through homodimeric IGF1Rs." (PMID 22438913, 2012). "The receptor tyrosine kinase insulin like growth factor-1 receptor (IGF-1R) and its ligands, IGF-1 and IGF-2, are essential for cell growth and development but also in the progression of various types of cancer, including HCC." (PMID 21569410, 2011). "MESOR of cortisol, TRH, GH, IL-2 and CD16 was increased in cancer patients, whereas MESOR of TSH, IGF-1, CD8, CD8bright, TcRδ1 and δTcS1 was decreased in cancer patients." (PMID 20565977, 2010). "Our study suggests a possible link between IGF-1 and DPP-IV in cancer development in a specific tumor niche." (PMID 23675206, 2010). "Survivin, an oncofetal protein with both pro-proliferative and anti-apoptotic properties, is a known transcriptional target of both IGF-1 and EGF in cancer cells." (PMID 20807437, 2010). "When we compared mean diurnal levels (mean of 06:00h-10:00h-14:00h) GH (p < 0.001) and CD16 (p < 0.01) levels were higher in cancer patients, whereas IGF1 (p < 0.001), CD8 (p = 0.03) and CD8bright (p = 0.001) levels were lower in cancer patients." (PMID 20565977, 2010). "MESOR of cortisol, TRH, GH, IL-2 and CD16 was increased, whereas MESOR of TSH, IGF-1, CD8, CD8bright, TcRδ1 and δTcS1 was decreased in cancer patients." (PMID 20565977, 2010). "This type of mechanism has been shown to increase lifespan and decrease cancer incidence in mutant dwarf mice, in which serum IGF-1 levels are greatly diminished, or in which the localized bioavailability of IGF-1 within tissues is reduced." (PMID 19968875, 2009). "Multiple growth factors such as IGF-1, VEGF, and EGF facilitate the development and progression of cancer by activating PI3K pathway leading to cell survival and therapeutic resistance." (PMID 19891769, 2009). "Mounting of evidence provided during the 10 last years implicates a crucial role of insulin-like growth factor 1 (IGF-1) signalling in development and progression of cancer." (PMID 15956962, 2005). "Recent findings have revealed that IGF1 is secreted locally by various cell types, depending on cancer cell behaviours rather than solely from the liver." (PMID 39796756, 2025).
cancer (continued). "The stimulatory loop formed by GHRH and its receptors can be blocked by GHRH antagonists, which exhibit antitumor functions across various cancer types, by directly inhibiting SV1 signaling or blocking tumor-derived insulin-like growth factor 1 (IGF1) and IGF2." (PMID 40244089, 2025). "IGF-1, along with insulin, activates the PI3K/AKT/mTOR pathway, promoting cell growth, proliferation, and survival while inhibiting apoptosis, which are key processes that support cancer cell development." (PMID 40566597, 2025). "It is important to mention that metastatic cancer cells secrete insulin-like growth factor binding protein-2 (IGFBP-2), a biomarker of human metastasis, which makes IGF-1 available in endothelial cells and activates the IGF-1 pathway." (PMID 41153350, 2025). "We also identify transcriptionally discrete iCAF phenotypes including a low activation/transition phenotype (IGF1+), likely the predominant iCAF in the current literature, as well as a more highly inflammatory IL11 + CAF subtype found within cancers of the GI tract." (PMID 39757146, 2025). "Insulin and IGF-1, both key players in metabolic regulation, share sequence similarities and can activate oncogenic signaling pathways such as MAPKs and PI3K-AKT, which are known to promote cancer cell proliferation and inhibit apoptosis." (PMID 40034825, 2025). "Tumor with HPD show reduced immunogenicity, increased immunosuppressive cells, mutations in cancer suppressor genes, and activation of ERK/MAPK, PI3K/AKT, TGF-β, and Insulin-like growth factor 1 (IGF-1) pathways, when compared to tumor without prior HPD." (PMID 40296912, 2025). "IGF‐1 then binds to its IGF‐1R, activating key oncogenic pathways such as PI3K/AKT/mTOR and MAPK/ERK, which drive cell proliferation, survival, and metabolic adaptation in cancer cells." (PMID 40387523, 2025). "Similarly, milk consumption raises circulating levels of insulin-like growth factor I (IGF-1), which stimulates cell proliferation and inhibits apoptosis in both normal and cancerous prostate cells." (PMID 41487662, 2025). "The role of IGF-1 and its associated binding proteins in cancer has not been fully elucidated, particularly the role of SKM-derived IGF-1 and IGFBPs." (PMID 38928185, 2024). "Furthermore, IGF-1 induces MUC1 expression, a glycoprotein engaged in multiple cancer-related pathways, via AKT signaling, promoting the translocation of β-catenin and EMT progression in MCF7 cells." (PMID 39273251, 2024). "The role of the IGF1/IGF1R axis in directly modulating MDSCs activity in cancer, has not yet been deeply investigated." (PMID 38420122, 2024). "Consequently, this decreases bioavailable IGF-1, inhibiting the growth of IGF-1-dependent cancers through endocrine, autocrine and/or paracrine signaling." (PMID 39417961, 2024). "On the contrary, downregulation of IGF-1 and upregulation of IGFBP-1, achieved through diet and exercise, may have protective effects against cancer cell development, depending on the type, intensity, and duration of training." (PMID 39555455, 2024). "Osteoclasts activity leads to the release of transforming growth factor-b (TGF-b), insulin-like growth-factor-1 (IGF-1), calcium, bone morphogenetic proteins (BMPs), fibroblast growth factors (FGF) in bone environment enabling cancer cell proliferation and survival." (PMID 39238997, 2024). "Analysis of Igf1 and Igf2 expression levels showed that epithelial plastic cancer cells did not induce the expression of these factors, suggesting a paracrine activation of IGF1R." (PMID 39075581, 2024). "The ligands for IGF1R (IGF1 and IGF2) are differentially expressed across pediatric cancers." (PMID 39510293, 2024). "αVβ3 (integrin αV:β3) is crucial in IGF‐1 (insulin‐like growth factor‐1) and FGF‐1 (fibroblast growth factor‐1) signaling, both of which are polypeptides involved in tumor progression of certain cancers." (PMID 38958135, 2024).
cancer (continued). "IGF-1 is known as a potent mitogen of high importance in the mammary gland that binds to the cognate receptor, IGF-1R, triggering a signaling intracellular cascade, which increases the proliferative and anti-apoptotic pathways in cancer cells." (PMID 38541726, 2024). "Emerging evidence suggests that insulin and its structurally similar counterpart, Insulin-like Growth Factor-1 (IGF-1), may play a role in malignant transformation and cancer progression through receptor activation." (PMID 38989325, 2024). "Furthermore, antibiotic mixture administration in mice led to reduced SCFA levels in feces, downregulation of both IGF1 and downstream MAPK and PI3K pathways, and inhibition of cancer growth." (PMID 39840030, 2024). "(E) SKM contractile activity-induced decreases in IGF-1, IGFBP-2, and insulin levels and increased IGFBP-1 and -3 levels may also help to limit cancer development in SKM." (PMID 38928185, 2024). "IGFs, particularly IGF-1 and IGF1R, significantly influence cancer biology." (PMID 39087024, 2024). "Circulating IGF-1 and IGFBP-2 are typically considered to be pro-tumorigenic; IGF-1 exhibits pro-proliferative and anti-apoptotic properties, while IGFBP-2 enhances cancer cell survival, proliferation, invasion, and migration, as well as intra-tumoral angiogenesis." (PMID 38928185, 2024). "The PEc expression may also explain the reduced efficiency of the anti-IGF-1 and anti-IGF-1R mAbs in various cancers." (PMID 39273251, 2024). "The 4 main signaling pathways previously implied to be linked to the impact of CR on life span, the insulin/ IGF-1, NF-ĸB, mTOR, and SIRT signaling pathways, showed no significant changes with the increase in CR level, neither did the pathways in cancer." (PMID 36757838, 2023). "IGF1/IGF1R regulates cell proliferation, angiogenesis, metastasis, metabolism, tumor microenvironment, chemoresistance, stem cells enrichment, and amplification in cancer." (PMID 36774408, 2023). "Particularly, IGF-1 binds to IGF-1R, a tyrosine kinase receptor, which activates its downstream signal effectors, comprising Ras/Raf/ERK and PI3K/Akt/mTOR, known to be involved in cell growth, proliferation, and in various types of cancers." (PMID 37509120, 2023). "No specific study was found to report the influence of glutamine, PUFAs, or other diet components on IGF-1 behavior neither in humans or dogs with cancer." (PMID 37410738, 2023). "Unfortunately, the IGF-1/PI3K/Akt signaling pathway also plays a critical role in tumor cell survival and proliferation, imposing a potential conflict when cancer therapy is imminent and physicians try to unravel tumor suppression and prevention of cardiotoxicity." (PMID 37655217, 2023). "Subsequently, tumor cells along with stromal cells generate various growth factors represented by epidermal growth factor receptor (EGFR) and insulin-like growth factor 1 (IGF-1) via autocrine and paracrine pathways to stimulate the continuous proliferation of cancer cells." (PMID 38067347, 2023). "Insulin-like growth factor 1 (IGF-1) and its IGF-1 receptor (IGF-1R) belong to an important biological system that is involved in the regulation of normal growth, but that has also been recognized as playing a role in cancer." (PMID 36891560, 2023). "We observed a decrease in plasma IGF-1 and EGF after surgery, varying among cancer types." (PMID 38067195, 2023). "Elevated levels of IGF-1 and IGF-2 are related to various cancers, including EC." (PMID 36761024, 2023). "The role of IGF-1 signaling is mainly explained by the mechanisms of increased proliferation, migration and cell survival via irradiated CAFs, which activate IGF-1R/AKT/mTOR signaling in cancer cells." (PMID 36835075, 2023). "These CAFs-derived molecules, IGF1/2, CXCL12 and beta-hydroxybutyrate, increased ROS level after radiation, thereby enhancing protein phosphatases 2A activity, inhibiting mTOR activation, and increasing autophagy in cancer cells." (PMID 37600785, 2023).
cancer (continued). "In patients with at least 1-year posttreatment GH and IGF-1 follow-up, the disease-controlled rate (45.5% vs. 45.9%) was similar between patients with cancer in any period (n = 88) or without cancers (n = 1147)." (PMID 37442901, 2023). "Furthermore, MP subtype cancer cells show high sensitivity to inhibition of the IGF1/IGF1R pathway, indicating specific therapeutic implications of targeting the IGF1/IGF1R pathway in specific GC patients." (PMID 36774408, 2023). "Low IGF-1 levels result in the inhibition of PI3K/Akt/mTOR system and of the synthesis of vascular endothelial growth factor (VEGF), which are involved in angiogenesis, cancer cell proliferation, and survival." (PMID 36139562, 2022). "The GHA mouse, transgenic for a GHRA and with reduced IGF1, mimics a pharmacologic inhibition of GHR and provides an excellent model to assess the effects of multiple chemotherapeutic efficacies in presence of a GHRA for multiple cancer types." (PMID 35865483, 2022). "IGFBP-1, a secreted phosphoprotein, is generally highly phosphorylated and inhibitory to IGF action; however a hypophosphorylated form of IGFBP-1 can potentiate IGF-1-mediated cell proliferation, and IGFBP-1 is known from non-cancer studies to promote migration through integrin signaling." (PMID 35597813, 2022). "Tumor stroma-derived insulin-like growth factor 1(IGF-1) and insulin-like growth factor binding protein (IGFBP) signaling have the potential to be novel targets for cancer therapy or adjuvant treatment, but these therapies have so far failed to yield significant efficacy." (PMID 35701840, 2022). "Although the IGF-1 signaling pathway in AC is poorly understood, many studies have proved that the IGF-1 signaling pathway could facilitate cancer cell survival." (PMID 36290805, 2022). "Since the relationship between serum IGF-1 and cancer was not always in consistency, we performed the detection of IGF-1 concentration in the serum of DM, DLB and DLC." (PMID 36329881, 2022). "In cancers with upregulation of IGF1R and circulating IGF-1 levels, tumor growth may be stimulated by IGF1R activation." (PMID 35597813, 2022). "Insulin, IGF-1 and IGF-2 could activate the PI3K/Akt/mammalian target of rapamycin (mTOR) signaling pathway, thereby promoting the development of cancers." (PMID 35222270, 2022). "Given the important role of these enzymes in cancer pathology, we hypothesized that UGT2B15 and UGT2B17 are novel targets for inhibitory regulation by IGF1." (PMID 35626664, 2022). "IGF1 enhances the hypoxic response by stabilizing HIF-α and upregulating VEGF-A.A functional cooperation between the IGF1R and VEGF pathways has been identified in cancer cells." (PMID 36479090, 2022). "However, more clinical studies are needed to evaluate the correlations among cancer, OSAHS, and IGF-1 levels." (PMID 36120463, 2022). "Similarly, insulin-like growth factor 1 (IGF1) initiates multiple signaling pathways including PI3K/AKT, MAPK, JAK/STAT, Src, and FAK, which stimulate cancer cell growth." (PMID 35565273, 2022). "As previously reported, exogenous IGF-1 sustains cell viability in cancer cell lines by stimulating mitochondrial biogenesis and BCL2 protein-interacting protein 3-like- (BNIP3-) induced mitophagy, and IGF-1 can also augment mitochondrial function and neuronal metabolism via AMPK." (PMID 36062186, 2022). "Our findings provide clues on the correlation between IGF-1/IGF-1R expression and cancer immunity and suggest that it could be a potential predictive maker of the efficacy of immunotherapy." (PMID 34804946, 2021). "In this review, we summarize the role of the circadian clock in regulation of one important metabolic pathway, insulin/IGF1/PI3K/mTOR signaling, and how dysregulation of this metabolic pathway could lead to uncontrolled cancer cell proliferation and growth." (PMID 33672910, 2021).